MUC5AC (mucin 5AC, oligomeric mucus/gel-forming)
Diseases named in the same sentence as MUC5AC in open-access papers (continued):
Sharing a sentence is not in itself a finding about the gene and the disease.
cholecystolithiasis (1 paper, 2013). Single or multiple, ovoid or irregular, solid particles that are formed from bile, cholesterol, and calcium in the gallbladder cavity. "It has been reported that the EGFR cascade causes MUC5AC overproduction in gallbladder epithelial cells and promoting stone formation in cholecystolithiasis." (PMID 24027752, 2013). "Meanwhile, EGFR activation is associated with MUC5AC overexpression in gallbladder epithelial cells which promotes stone formation in cholecystolithiasis." (PMID 24027752, 2013). "However, because of the differences between cholecystolithiasis and hepatolithiasis and the heterogeneity between gallbladder and intrahepatic epithelial cells, whether EGFR activation is involved in MUC5AC overproduction in intrahepatic biliary epithelial cells needs to be investigated further." (PMID 24027752, 2013).
chronic asthma (1 paper, 2022). An asthma that is characterized by the development of persistent airway inflammation and recurrent attacks of breathlessness and wheezing, which vary in severity and frequency. "The quasi-absence of goblet cell hyperplasia and the reduced gene expression of Muc5ac, a gene linked to mucus secretion, in the MSC-treated IL-13 TG mice also indicated that Liproxstatin-1-primed hUC-MSCs exert anti-inflammatory effects in a murine model of chronic asthma." (PMID 35697721, 2022).
chronic lung disease (1 paper, 2016). According to the definitions of the American and British Thoracic Societies, including pulmonary functional tests, X-rays, and CT scans for items such as fibrosis, bronchiectasis, bullae, emphysema, nodular or lymphomatous abnormalities. "MUC5AC, known as tracheobronchial mucin, is a major mucin of lung mucus and is abundantly expressed during acute and chronic lung diseases and thereby greatly contributes to disease morbidity and mortality." (PMID 27034593, 2016).
clostridium difficile infection (1 paper, 2022). Symptomatic infection due to the spore-forming bacterium clostridium difficile. "Particularly, Helicobacter pylori and Clostridium difficile infections are associated with disrupted mucin synthesis and mucus barrier, whereas Helicobacter pylori-infected patients present with a significant decrease in MUC5AC gene expression levels." (PMID 35745251, 2022).
duodenal cancer (1 paper, 2025). "Our case showed MUC5AC and MUC6 staining in the duodenal cancer." (PMID 41098299, 2025).
Dyskinesia (1 paper, 2023). A movement disorder which consists of effects including diminished voluntary movements and the presence of involuntary movements. "During the repair of the injured mucociliary epithelium in the ALI system, silica-induced NLRP3 inflammasome activation led to either MUC5AC or MUC5B overproduction, multiciliogenesis, and ciliary disorientation, structural defects and dyskinesia." (PMID 37063430, 2023).
endometrial adenocarcinoma (1 paper, 2017). "MUC5AC was found to be up-regulated in endometrial adenocarcinoma compared with normal endometrium or endometrial hyperplasia." (PMID 28938681, 2017).
esophageal cancer (1 paper, 2025). A primary or metastatic malignant neoplasm involving the esophagus. "The prognostic significance of these mucins is also partially different in the two tumor types, with MUC5AC being more helpful in gastric and CEA in esophageal cancers." (PMID 40699805, 2025).
food allergy (1 paper, 2022). Gastrointestinal disturbances, skin eruptions, or shock due to allergic reactions to allergens in food. "Within these, 113 genes (27.8%) have been previously associated with food allergy; within the top 10 DE genes, 8 genes have been previously linked to food allergy—C3, CXCL8, RARRES1, CXCL6, MUC5AC, CXCL1, and SAA3." (PMID 36452260, 2022).
gallbladder dysplasia (1 paper, 2023). "A few studies show mature MUC5AC (detected with 45M1 antibodies) is upregulated in gallbladder dysplasia, biliary dysplasia, and gallbladder pyloric gland adenoma." (PMID 36672382, 2023). "Immature MUC5AC (detected by CLH2 antibodies) is upregulated in many BTC precursor neoplasms such as biliary intraepithelial neoplasia (BilIN), intraductal papillary neoplasm of the bile duct (IPNB), gallbladder dysplasia, biliary dysplasia, and intraductal papillary neoplasm of the liver (IPNL)." (PMID 36672382, 2023).
gastric mucinous adenocarcinoma (1 paper, 2020). "Moreover, 24 out of 26 cases of gastric mucinous adenocarcinoma expressed MUC5AC, and 23 of them were CK7 positive (P = 0.448)." (PMID 32843061, 2020).
gastric papillary adenocarcinoma (1 paper, 2024). A variant of gastric adenocarcinoma with exophytic growth and elongated finger-like processes lined by cylindrical or cuboidal cells supported by fibrovascular connective tissue cores. "Clinically, gastric papillary adenocarcinoma typically overexpresses the gastric phenotype mucins MUC5AC and MUC6, which may aid in distinguishing between EGDTA and EGPA." (PMID 39540152, 2024).
gastric squamous cell carcinoma (1 paper, 2025). A rare carcinoma of the stomach resembling squamous cell carcinomas arising elsewhere in the body. "In the present case, focal positivity of CK7 and MUC5AC was initially detected by immunohistochemistry, which led to the misdiagnosis of gastric squamous cell carcinoma." (PMID 41333217, 2025). "This abnormal differentiation may also occur in gastric squamous cell carcinoma, leading to focal positivity of adenocarcinoma related markers such as MUC5AC." (PMID 41333217, 2025).
hearing loss (1 paper, 2023). "MUC5ac overexpression has been associated with hearing loss, although paradoxically it was upregulated in the young locust." (PMID 37274746, 2023).
hepatoid adenocarcinoma (1 paper, 2009). An adenocarcinoma with morphologic characteristics similar to hepatocellular carcinoma, arising from an anatomic site other than the liver. "Four phenotypic categories according to the inmunohistochemical results for CD10, MUC2, MUC5AC, and MUC6 were described for both components, tubular adenocarcinomatous and hepatoid, of hepatoid adenocarcinoma." (PMID 19674468, 2009). "In contrast, no gastric phenotype (MUC5AC+, MUC6+, MUC2-, CD10-) was observed in any of the hepatoid adenocarcinoma components." (PMID 19674468, 2009).
intestinal infections (1 paper, 2021). "While MUC5AC is considered protective, alterations in the MUC1 expression in both directions have been associated with intestinal infections and inflammation." (PMID 34685068, 2021).
intraepithelial neoplasia (1 paper, 2023). A precancerous neoplastic process that affects the squamous, glandular, or transitional cell epithelium without evidence of invasion.
mucinous cystadenoma (1 paper, 2019). A benign or low malignant potential cystic epithelial neoplasm composed of cells which contain intracytoplasmic mucin. "On the contrary, 100% primary mucinous cystadenomas, borderline tumors, and carcinomas were positive for MUC5AC." (PMID 31689847, 2019).
mucoepidermoid carcinoma (1 paper, 2022). A carcinoma morphologically characterized the presence of cuboidal mucous cells, goblet-like mucous cells, squamoid cells, cystic changes, and a fibrotic stromal formation. "Consistent with our data, it has been reported that verproside reduces the TNF-α-induced activity of NF-κB, resulting in suppression of TNF-α-induced MUC5AC expression in pulmonary mucoepidermoid carcinoma cells." (PMID 36670877, 2022).
oral cavity cancer (1 paper, 2020). A primary or metastatic malignant neoplasm involving the oral cavity.
oral disease (1 paper, 2022). "Upregulation of the building blocks of secretory airway mucus, gel forming mucin 5AC and mucin 5B (MUC5AC, MUC5B), is a common symptom of both respiratory and oral disease state." (PMID 36146663, 2022).
osteoarthritis (1 paper, 2025). A noninflammatory degenerative joint disease occurring chiefly in older persons, characterized by degeneration of the articular cartilage, hypertrophy of bone at the margins and changes in the synovial membrane. "Furthermore, OBS has been shown to regulate MUC5AC mucus mRNA expression and synthesis in airway epithelial cells by modulating the NFκB pathway, and to reduce inflammation in an osteoarthritis model via NFκB signaling inhibition." (PMID 39976722, 2025).
otitis media (1 paper, 2022). Inflammation of the anatomical structures of the middle ear, which is most often caused by an infectious process. "Moreover, upregulation of Muc5ac and Muc5b in Galnt2 mutant mice resulted in increased middle ear effusion and decreased mucociliary clearance, thereby preventing otitis media." (PMID 36874359, 2022).
Ovarian cyst (1 paper, 2015). The presence of one or more cysts of the ovary. "In this study, we analyzed the expression of the MUC5AC and the O-glycosylation of acidic glycoproteins secreted into ovarian cyst fluids." (PMID 26075384, 2015).
pancreatic disease (1 paper, 2025). "For pancreatic disease, differential expressions of MUC5AC are observed in patients with benign pathologies, chronic pancreatitis, and PC." (PMID 40363817, 2025). "MUC5AC has been validated as a potential pancreatic disease biomarker in tissue in independent studies." (PMID 40363817, 2025).
Pleural effusion (1 paper, 2025). The presence of an excessive amount of fluid in the pleural cavity. "Furthermore, a further ROC curve analysis was conducted using risk factors (sputum MUC5AC level, maximum temperature, presence of pleural effusion, and serum LDH, NLR, and IgM) as predictors to predict risk for requiring fiberbronchoscopy treatment." (PMID 40600698, 2025). "Stepwise regression analysis revealed that the maximum temperature, presence of pleural effusion, NLR, the level of LDH in serum, sputum MUC5AC level, and serum IgM were independent risk factors for requiring fiberbronchoscopy treatment (all P < 0.05)." (PMID 40600698, 2025).
pneumococcal meningitis (1 paper, 2025). An acute purulent infection of the meninges and subarachnoid space caused by Streptococcus pneumoniae, most prevalent in children and adults over the age of 60. "CCL20 can recruit Th17 cells, B cells, and dendritic cells, recruit granulocytes in pneumococcal meningitis, can have antimicrobial activity, and could induce MUC5AC mucin production in a human airway epithelial cell line." (PMID 40586572, 2025).
prostate tumour (1 paper, 2004). "Using PAC120, a xenograft of a human hormone-dependent prostate tumour, and its hormone-independent variants, we analysed the expression of mucins (MUC1, MUC2, MUC4, MUC5AC, MUC5B, MUC6) by immunohistochemistry or reverse transcriptase (RT)–PCR." (PMID 14760390, 2004).
salivary gland carcinoma (1 paper, 2022). A carcinoma that arises from the major or minor salivary glands. "The current study aimed to determine the expression rate of Mucin-1 (MUC1), Mucin-16 (MUC16), and Mucin-5AC (MUC5AC) in salivary gland carcinomas (SGC) using immunohistochemistry." (PMID 35389164, 2022). "MUC5AC seems not to qualify as a molecular target for salivary gland cancer therapy." (PMID 35389164, 2022).
serous ovarian cancer (1 paper, 2015). "al showed mRNA expression of MUC5AC in both mucinous and serous ovarian cancer tissues by Northern blotting analyses." (PMID 26075384, 2015).
serous ovarian tumor (1 paper, 2015). "With the exception of one LMP tumor with low reactivity, all serous ovarian tumors showed an absence of immunoreactivity toward MUC5AC antibodies." (PMID 26075384, 2015).
spasm (1 paper, 2022). "As for quercetin, existing studies have indicated that quercetin relieves asthmatic tracheal spasm by inhibiting the expression of MUC5AC in airway epithelial cells and improves allergic inflammation by regulating TH1/TH2 balance and reducing antigen-specific IgE antibodies." (PMID 35855823, 2022).
status asthmaticus (1 paper, 2007). An acute exacerbation of asthma, characterized by inadequate response to initial bronchodilators. "However, biochemical studies on human samples have shown that the aberrant physical properties of the mucus gel obstructing the airways from an individual that died in status asthmaticus are due to MUC5B and not MUC5AC." (PMID 17550583, 2007).
ventilator-associated pneumonia (1 paper, 2019). Serious INFLAMMATION of the LUNG in patients who required the use of PULMONARY VENTILATOR. "MUC5AC over-expression has been observed in patients with chronic respiratory diseases and ventilator-associated pneumonia (VAP)." (PMID 31849655, 2019).
Zinc deficiency (1 paper, 2020). A deficiency of the essential metal Zinc; an essential cofactor for many enzymes. "Synthesis and secretion of mucins were severely disturbed during zinc deficiency, affecting both MUC2 and MUC5AC mRNA expression with ongoing cell differentiation." (PMID 32858966, 2020).
tumor (208 papers, 2004 to 2025). "ST6GalNAc-I– and MUC5AC–deficient tumors showed reduced tumor incidence, tumor angiogenesis, and liver metastasis." (PMID 40371640, 2025). "The expression of MUC5AC is closely associated with tumor aggressiveness and poor prognosis in various types of cancer." (PMID 40655139, 2025). "The quantity and intensity of cellular interactions among PGA3+ tumor cells in cluster 0, MUC5AC+ tumor cells from cluster 1, TFF3+ tumor cells associated with cluster 2, and other diverse cell types were then illustrated." (PMID 40124374, 2025). "One study using mature MAN-5ACI antibodies associated MUC5AC-positive tumors with more advanced TNM tumor staging and increased frequency of perineural invasion." (PMID 36672382, 2023). "The downregulation of AQP1 appeared to be closely linked to the expression of MUC5AC and the aggressive behavior of the tumor." (PMID 37904849, 2023). "Our gene-expression data reveal that low level of KChIP3, which negatively regulates baseline secretion, is an important risk factor for untreated tumours with high MUC5AC expression levels." (PMID 35131032, 2022). "The PB subtype express a considerable number of markers, including cytokeratins (CK7, CK17, and CK19), mucins (MUC1 and MUC5AC), and tumor-associated epithelial markers (CA19-9, monoclonal CEA, CA125, and maspin)." (PMID 36358777, 2022). "In this context, MUC5AC was aberrantly expressed in tumor tissue and associated with larger tumor size and advanced stage in liver fluke-associated CCA." (PMID 35205774, 2022). "MUC5AC was additionally associated with right-sided tumor location (p = 0.01), higher pT (p = 0.0073), more frequent distant metastasis (p = 0.0334), higher tumor grade (p < 0.0001), frequent BRAF mutation (p < 0.0001) and MMR-deficiency (p < 0.0001)." (PMID 34475526, 2022). "As for MUC5AC, its tumor-associated expression represents another example of dysregulated neoplastic cell-fate differentiation." (PMID 33423702, 2021). "MUC5AC plays a role by influencing various critical pathways implicated in the malignant transformation and tumor progression in PDA, and the effects are pathway-specific." (PMID 34205412, 2021). "In this study, MUC5AC expression was firstly found to be up-regulated in patients with ccRCC, positively associated with tumor size, pN stage, Fuhrman grade, LVI, rahbdoid differentiation, sarcomatoid features, tumor necrosis, ECOG-PS and recurrence." (PMID 28938681, 2017). "MUC5AC expression was firstly found to be up-regulated in patients with ccRCC, positively associated with tumor size, pN stage, lymphovascular invasion, Fuhrman grade, rahbdoid differentiation, sarcomatoid features, tumor necrosis, ECOG-PS and recurrence." (PMID 28938681, 2017). "According to their and other literature data, MUC6 and MUC5AC expression is strongly associated with features of the serrated neoplasia pathway." (PMID 27298226, 2016). "The knockdown studies revealed that MUC5AC overexpression in tumor cells is associated with increased growth, adhesion, invasion of tumor cells and increased metastatic tendency." (PMID 24722639, 2014). "The positive expression of MUC1 was the highest of the four mucins investigated, and the expressions of MUC1 and MUC5AC were associated with levels of tumor aggressiveness." (PMID 22027009, 2011). "It is likely that the loss of cell orientation in advanced neoplasia results in ‘spilling’ of the normally apically secreted MUC5AC mucin into the circulation, which was then detectable with the more sensitive polyclonal Lum5-1 antibody." (PMID 18475301, 2008). "In pancreatic malignancy, MUC4 is a diagnostic and prognostic tumour marker, whereas MUC5AC has been proposed as a sensitive serological marker for BTC." (PMID 18475301, 2008).